ENSG00000206976
Gene: Small nucleolar RNA gene on chromosome 11 (3,922,567 to 3,922,703, forward strand). Ensembl gene ENSG00000206976.
Homologues: Paralogues in human: SNORA7A (87% identical), SNORA7B (87% identical).